ANGPTL4 (angiopoietin like 4)
Diseases named in the same sentence as ANGPTL4 in open-access papers (continued):
Sharing a sentence is not in itself a finding about the gene and the disease.
pancreatic cancer (15 papers, 2015 to 2025). "In pancreatic cancer, ANGPTL4 overexpression has been associated with tumorigenesis, cellular resistance to chemotherapy, hypoxia response, and poor patient outcomes." (PMID 37291514, 2023). "ANGPTL4 is highly expressed in pancreatic cancer tumor tissues and is associated with the progression of pancreatic cancer." (PMID 37762693, 2023). "In summary, over-expression of ANGPTL4 in fibroblasts promotes pancreatic cancer cell proliferation, migration, and would healing through paracrine mechanism, but does not enhance these processes in fibroblasts themselves via an autocrine pathway." (PMID 39811640, 2025). "ANGPTL4, a key adipogenesis regulator, was highly expressed in fibroblasts and promoted pancreatic cancer cell proliferation and migration through paracrine signaling." (PMID 39811640, 2025). "The overexpression of ANGPTL4 in fibroblasts induces pancreatic cancer cell proliferation, migration, and wound healing in paracrine manner, while not exhibiting autocrine effects within the fibroblasts themselves." (PMID 39811640, 2025). "Our study provides evidence that ANGPTL4 overexpression in pancreatic cancer impacts several key signaling and metabolic pathways associated with patient survival, in part through controlling cellular resistance to chemotherapy and cellular migration." (PMID 37291514, 2023). "Here we have described how overexpression of ANGPTL4 in pancreatic cancer contributes to disease progression and resistance." (PMID 37291514, 2023). "Our transcriptomic analysis revealed that overexpression of ANGPTL4 broadly impacts transcriptomic profiles in pancreatic cancer cells." (PMID 37291514, 2023). "The complicated role for ANGPTL4 motivates our further exploration of its function in pancreatic cancer." (PMID 37291514, 2023). "We measured the impact of ANGPTL4 overexpression in a common pancreatic cancer cell line, MIA PaCa-2 cells, using CRISPRa for overexpression and DsiRNA for knockdown." (PMID 36747689, 2023). "Immunohistochemical analysis of ANGPTL4 in human pancreatic cancer samples showed broad positivity." (PMID 39811640, 2025). "However, when we applied conditional medium from OV_ANGPTL4 fibroblasts to PANC-1 pancreatic cancer cells, we observed a significant increase in cancer cell proliferation, migration, and would healing, compared to medium from control fibroblasts." (PMID 39811640, 2025). "Given that cancer cell-driven paracrine signals appear to regulate Angptl4 expression in fibroblasts, ANGPTL4 may act as a reciprocal factor, creating a feedback loop that supports pancreatic cancer progression." (PMID 39811640, 2025). "Increased expression of ANGPTL4 in tumors correlates with poor outcomes in pancreatic cancer." (PMID 36747689, 2023). "In addition, some researchers believe ANGPTL4 is closely related to the prognosis of malignant tumours, such as thyroid, cervical, and pancreatic cancer." (PMID 36467503, 2022). "This suggests that factors secreted by cancer cells may play a crucial role in modulating ANGPTL4 expression in fibroblasts, indicating that ANGPTL4 could function as a reciprocal factor that contributes to a feedback loop promoting pancreatic cancer progression." (PMID 39811640, 2025). "Hence, it may be possible that ANGPTL4 plays a role in downregulating ECM-related genes in pancreatic cancer." (PMID 39811640, 2025). "ANGPTL4 may play a role in creating a feedback loop that supports pancreatic cancer progression, while the down-regulation of the ECM protein LAMA2 is likely associated with pancreatic cancer advancement." (PMID 39811640, 2025). "However, the precise function and role of ANGPTL4 in pancreatic cancer is still unclear." (PMID 26294325, 2015). "In conclusion, our findings demonstrate a consistent up-regulation of Angptl4 in stromal fibroblasts during early-stage pancreatic carcinogenesis in KPC mice and human pancreatic cancer." (PMID 39811640, 2025).
pancreatic cancer (continued). "Our data from co-culture experiments of KPC fibroblasts with primary pancreatic cancer cells also showed an increase in Angptl4 expression compared to KPC fibroblasts without co-culture." (PMID 39811640, 2025).
renal cell carcinoma (14 papers, 2005 to 2025). "Preclinical and clinical data previously showed that ANGPTL4 is expressed in the hypoxic areas of human renal cell carcinoma, and promotes angiogenesis and tumorigenesis." (PMID 32695883, 2020). "However, another early study reported that ANGPTL4 could promote angiogenesis in ischemic tissues or solid tumor tissues (conventional renal cell carcinoma) due to the existence of hypoxia." (PMID 36553482, 2022). "To further confirm the tumor growth suppressive function of ANGPTL4, we generated Renca mouse renal cell carcinoma cells with WT VHL, which express V5-tagged ANGPTL4 (Renca-A4)." (PMID 39105498, 2024). "ANGPTL4 belongs to the angiopoietin (ANGPTL) family and the clinical and prognostic significance of serum ANGPTL4 has been reported in renal cell carcinoma." (PMID 35392474, 2022). "Similarly to previous observations of induced angiopoietins in primary renal cell carcinomas (ANGPT2 8.18-fold induced and ANGPTL4 18–32-fold induced, we found both ANGPTL4 induction (2.09 fold, Pcorr < 2e-9), and ANGPT2 induction (2.23-fold Pcorr < .005)." (PMID 15836779, 2005).
prostate carcinoma (13 papers, 2005 to 2025). A carcinoma that arises from epithelial cells of the prostate gland. "Higher ANGPTL4 levels in prostate cancer tissue have been associated with worse overall survival rates." (PMID 38791417, 2024). "Though various reports have focused on various forms of cancer, this study lays credence to the discovery of the possible implication of ANGPTL4 in prostate cancer and its key association with a high Gleason score and radiomic features." (PMID 37048688, 2023). "More than half of patients in the present study displayed immunoreactivity for ANGPTL4 (67%), this in concordance with previous studies investigated ANGPTL4 expression in breast and prostate cancer tissues." (PMID 35366286, 2022). "And the expression of ANGPTL4 in prostate cancer can be used as a clinical prognostic marker and therapeutic target." (PMID 34331381, 2021). "ANGPTL4 plays a role in angiogenesis, the process of blood vessel development, and its increased expression has been observed in several malignancies, including prostate cancer." (PMID 38791417, 2024). "Hence, ANGPTL4 represents a potential therapeutic target in the treatment of prostate cancer, it may be possible to disrupt tumor growth and survival mechanisms, offering a novel approach for the treatment of prostate cancer." (PMID 38694500, 2024).
colon carcinoma (12 papers, 2010 to 2025). "In multivariable-adjusted Cox proportional hazards models, lower colon tumor ANGPTL4 gene expression was associated with reduced risk of all-cause mortality (HR per log2 decrease = 0.85, 95% CI = 0.73 to 0.99; P = .04)." (PMID 40511612, 2025). "Finally, in analysis of 465 colon cancer patients, lower ANGPTL4 expression in colon tumor tissue was associated with a reduced risk of all-cause mortality." (PMID 40511612, 2025). "Finally, we evaluated the association of colon tumor ANGPTL4 expression with cancer-specific mortality in TCGA." (PMID 40511612, 2025). "Finally, to explore whether ANGPTL4 is involved in cancer progression, we evaluated the association of ANGPTL4 gene expression in colon tumor tissue with all-cause mortality in The Cancer Genome Atlas (TCGA)." (PMID 40511612, 2025). "Recombinant ANGPTL4 has been reported to promote colon cancer growth by impairing CD8+ T cell activity in mice." (PMID 40511612, 2025). "The overexpression of Angptl4 promotes colon cancer cell migration through the cytoskeletal signalling pathway, while the downregulation of ANGPTL4 impairs tumour growth and metastasis." (PMID 26508818, 2015). "The colon carcinoma cell line HCT116 was used to determine effects of selected gut microbiota on ANGPTL4 expression in colonocytes." (PMID 20927337, 2010). "We also performed experiments to confirm the effects of ANGPTL4 on colon cancer cell lines." (PMID 36553482, 2022). "For example, ANGPTL4 is positively correlated with CD8+ T cells and endothelial cells in both colon cancer and rectal cancer." (PMID 36553482, 2022). "Stimulation of cultured human colonic cancer epithelial (CaCo-2) cells with 5-ASA induced expression of PPARG and the PPAR-γ-activated gene ANGPTL4 and triggered synthesis and the nuclear localization of PPAR-γ." (PMID 33468700, 2021).
ischemic stroke (11 papers, 2018 to 2025). A stroke disorder caused by obstruction of blood flow to the brain, due to thrombotic (local blood clot formation) or embolic (due to a blood clot or other material traveling from another site) event. "Mouse studies further suggested that Angptl4 counteracted the loss of vascular integrity and protected the permeability of the blood–brain barrier damaged by ischemic stroke." (PMID 37533068, 2023). "The RNASeq analysis revealed that expression of ANGPTL4, previously found to be associated with ischemic stroke, was particularly elevated in mtDNA haplogroup F1 after hypoxic-ischemic stress." (PMID 32796743, 2020). "FAP encodes fibroblast activation protein alpha, which has been reported to be associated with inflammation and stroke; meanwhile, ANGPTL4 encodes angiopoietin-like 4, a protein expressed in vascular endothelial cells, which may have an influence on vascular atherosclerosis and ischemic stroke." (PMID 32796743, 2020). "Previously, MR methods have been used to investigate the causal relationship of circulating protein biomarkers on ischemic stroke and the impact of angiopoietin-like protein 3 (ANGPTL3) and 4 (ANGPTL4) inhibition of lipoprotein lipase (LPL) on CVD." (PMID 40904650, 2025). "Although the role of ANGPTL4 in ischemic stroke remains inconclusive, recent studies have identified elevated protein expressions of ANGPTL4 in stroke patients." (PMID 32796743, 2020). "A recent work has demonstrated a protective effect of ANGPTL4 on the BBB after ischemic stroke injury and reperfusion by thrombolysis." (PMID 31766605, 2019). "Animal experiments also revealed that ANGPTL4 promotes neovascularization in ischemic stroke mice." (PMID 39470400, 2024). "Furthermore, we have detected Angiopoietin-like 4, which supported neurogenesis in an ischemic stroke rodent model, Decorin, which supported axon growth in the SCI model, as well as CSF1." (PMID 38025267, 2023). "Angptl4 modulates BBB dysfunction in ischemic stroke and is neuroprotective." (PMID 29495967, 2018). "Therefore, to test the potential use of serum ANGPTL4 levels as a biomarker for correlative diagnosis of acute ischemic stroke, we analyzed the serum levels in blood samples taken from a small cohort of patients within one day of an ischemic stroke event." (PMID 32796743, 2020). "However, there is no universal agreement on the association between the ANGPTL4 variants and serum lipid traits, and the risk of CAD and ischemic stroke (IS) in different populations." (PMID 30323852, 2018).
Stroke (11 papers, 2014 to 2025). Sudden impairment of blood flow to a part of the brain due to occlusion or rupture of an artery to the brain. "For example, HDAC9 or ANGPTL4 variants not only identify stroke susceptibility but also inform possibilities for repurposing HDAC inhibitors or enhancing ANGPTL4-mediated protection." (PMID 40863347, 2025). "Our study identified astrocyte-specific differential expression of SPP1 and ANGPTL4, highlighting their crucial role in post-stroke angiogenesis." (PMID 40988927, 2025). "Specifically, PPARα KO led to increased expression levels of Gadd45b, Nppa, Hdc, Lcn2, Il6, Sox4, Marcksl1, Saa3, Ucn2, Met, Dusp10, Elovl7, Ngf, C3, Il11, Hmox1, Alox5, Tnfsf9, Angptl4, Plin2, H19, Csf2rb, Atf3, and Col7a1 following stroke." (PMID 40362325, 2025). "In this regard, serum ANGPTL4 levels in a series of 712 patients with stroke due to large artery atherosclerosis disease were significantly higher than those in 828 controls after adjustment for other risk factors." (PMID 35488290, 2022). "ANGPTL4 was found to be involved in angiogenesis and vessel sprouting in a rat stroke model and was also shown to have a vasculoprotective effect in a mouse stroke model." (PMID 32980981, 2021). "Many clinical studies have suggested using Angptl4 for post-stroke treatment because it could enhance angiogenesis and neurogenesis by reducing neuronal death and inflammatory response." (PMID 37533068, 2023). "Literature reports that ANGPTL4 upregulation corresponds to increased vascularization after stroke." (PMID 28097054, 2017). "It has been reported that ANGPTL4 serum levels may increase during a stroke event." (PMID 32796743, 2020). "Third, an important limitation of our study is that serum ANGPTL4 level was not measured in stroke patients before the onset of AIS." (PMID 39972951, 2025).
head and neck squamous cell carcinoma (10 papers, 2017 to 2025). A squamous cell carcinoma that arises from any of the following anatomic sites: lip and oral cavity, nasal cavity, paranasal sinuses, pharynx, larynx, and salivary glands. "The ANGPTL4/NOX4 axis is critical for tumor cell extravasation and metastatic seeding of tumor cells in dyslipidemia-associated cancer like kidney cancer, head and neck squamous cell carcinoma and so on." (PMID 36829161, 2023). "Induction of molecules involved in the regulation of EMT was earlier shown as dependent on ANGPTL4 expression in head and neck squamous cell carcinoma cells." (PMID 34405010, 2021). "In giant cell tumor and head and neck squamous cell carcinoma, ANGPTL4 benefits cancers by inducing cell proliferation, angiogenesis, anoikis resistance, and metastasis." (PMID 31717924, 2019). "ANGPTL4 has also been revealed to enhance anoikis resistance and tumor metastasis via the upregulation of MMP‐1 expression in head and neck squamous cell carcinoma." (PMID 36507553, 2023). "In head and neck squamous cell carcinoma, EGF regulates metastasis through the induction of angiopoietin-like 4 (ANGPTL4), which was inhibited after genetic or pharmacological inhibition of COX-2." (PMID 37190301, 2023). "On the one hand, OA-induced recombinant angiopoietin like protein 4 (ANGPTL4) could promote the anoikis resistance and metastasis of head and neck squamous cell carcinoma through upregulating fibronectin." (PMID 39875372, 2025).
Nephropathy (10 papers, 2014 to 2026). A nonspecific term referring to disease or damage of the kidneys. "In recent years, studies have shown that increased Angptl4 secreted by podocytes is an important pathogenic factor leading to podocyte injury in kidney diseases, especially minimal change disease and DN." (PMID 40256245, 2025). "This review summarizes the abnormal expression of ANGPTL4 in various kidney diseases, its specific mechanisms, and its pathogenic functions." (PMID 39840089, 2024). "Our previous study also observed an important role of Angptl4 in podocyte injury-associated nephropathy." (PMID 33643055, 2020). "However, another study showed that urinary ANGPTL-4 was elevated in patients with colossal proteinuria despite the underlying renal disease." (PMID 37108963, 2023). "Elevated levels of ANGPTL4 contribute to vascular permeability, a hallmark of diabetic retinopathy, while ANGPTL8 has been linked to nephropathy progression." (PMID 40137149, 2025). "This review synthesizes the available literature, provides a concise overview of the molecular biological effects of ANGPTL4, and highlights its relationship with multiple renal diseases and recent research advancements." (PMID 39840089, 2024). "Numerous studies have elucidated the potential roles of ANGPTL4 in these renal disorders, underscoring the need for a systematic review and analysis of existing research to better understand its role." (PMID 39840089, 2024). "In summary, the mechanistic role of ANGPTL4 in renal diseases, particularly proteinuric disorders, is complex and multifaceted." (PMID 39840089, 2024). "To date, extensive research has demonstrated that ANGPTL4 is aberrantly expressed in various kidney diseases and is closely related to the progression of these conditions through multiple mechanisms." (PMID 39840089, 2024). "Large proteomic studies identified angiopoietin-like protein 4 (Angptl4) and angiostatin as useful urinary biomarkers for tracking renal disease activity and kidney pathology in patients with SLE." (PMID 36233628, 2022). "Collectively, our correlation analysis displayed a clear link between the rise in circulating ANGPTL4 and kidney disease." (PMID 31772941, 2019). "Thus, recombinant mutant human ANGPTL4 is being developed as a promising therapeutic approach for nephropathy." (PMID 39840089, 2024). "Over the past 2 decades, ANGPTL4 has been regarded as playing a pivotal role in the progression of various kidney diseases, prompting significant interest from the scientific community regarding its potential clinical utility in renal disorders." (PMID 39840089, 2024). "Interestingly, this elevation is specific to the renal disease state, with comparable ANGPTL4 levels in type 2 diabetes patients and controls." (PMID 39840089, 2024). "Studies investigating ANGPTL4 in T2D and nephropathy are limited." (PMID 31772941, 2019). "In our study population, elevated levels of ANGPTL4 were restricted to a condition of nephropathy and it was significantly correlated with clinical markers of DN, suggesting ANGPTL4 as a parameter that would help in characterizing a condition of the diabetic nephrotic syndrome." (PMID 31772941, 2019). "It would also be interesting to measure levels of ANGPTL4 in nondiabetic kidney disease patients, to understand if the ANGPTL4 elevation is specific to DN or is a feature of any kidney disease." (PMID 31772941, 2019). "Angiopoietin-like protein 4 (ANGPTL4) is a multifunctional cytokine involved in the regulation of key biological processes, such as glucose and lipid metabolism, inflammation, vascular permeability, and angiogenesis, all of which play crucial roles in the pathogenesis of kidney diseases." (PMID 39840089, 2024). "In addition to ANGPTL4, other members of the ANGPTL family play critical roles in renal diseases." (PMID 39840089, 2024).
Nephropathy (continued). "However, this study has some limitations, as Angptl4 has an effect on podocyte damage in many kidney diseases, it is not specific to IgAN, and the size of biopsies of patients with IgAN used for expression was small." (PMID 33643055, 2020). "Increasing evidence shows that Angptl4 affects proteinuria in podocytes injured kidney disease, however, whether there is a relationship between Angptl4 and IgA nephropathy (IgAN) has not been studied yet." (PMID 33643055, 2020).